POU5F1P4 (POU class 5 homeobox 1 pseudogene 4)
Synonyms: POU5FLC1; Oct4-pg4
Gene: Processed pseudogene on chromosome 1 (155,433,178 to 155,434,262, forward strand). Ensembl gene ENSG00000237872.
Diseases named in the same sentence as POU5F1P4 in open-access papers:
POU5F1P4 is named in the same sentence as 10 diseases in open-access papers, as found by Europe PMC text mining. Sharing a sentence is not in itself a finding about the gene and the disease. The quoted sentences say what the papers report.
colorectal cancer (2 papers, 2018 to 2023). A primary or metastatic malignant neoplasm that affects the colon or rectum. "By contrast, the result from the R2: Genomics analysis and visualization platform showed that high expression of POU5F1P4 was associated with a poor prognosis in colorectal cancer, further suggesting that expression of POU5F1P4 regulates both cancer progression and clinical outcomes." (PMID 30287838, 2018). "POU5F1P3 and POU5F1P4 are oncogenes in kidney and colorectal cancer, respectively." (PMID 37667739, 2023). "The results revealed the potential signaling of POU5F1P4 involved in breast and colorectal cancers." (PMID 30287838, 2018). "POU5F1P4 expression may also play a role in olfactory transduction and the Wnt signaling pathway in colorectal cancer." (PMID 30287838, 2018). "Similarly, the three OCT4 pseudogenes normally function as tumor suppressor genes in various cancer types, while POU5F1P3 in kidney cancer and POU5F1P4 in colorectal cancer may function as oncogenes." (PMID 30287838, 2018).
breast carcinoma (1 paper, 2018). "In breast cancer, the predominant signaling pathway regulating POU5F1P4 is the metabolic pathway, which showed the highest level of significance." (PMID 30287838, 2018). "We identified the co-expression profile of POU5F1P4 across 53 breast cancer and 6 normal tissues." (PMID 30287838, 2018). "Particularly, in breast cancer, expression of OCT4, POU5F1P3, and POU5F1P4 was down-regulated compared to in normal tissue." (PMID 30287838, 2018).
gastric cancer (1 paper, 2018). A primary or metastatic malignant neoplasm involving the stomach. "Specifically, the results from the PrognoScan and Kaplan Meier-plot databases showed that the poor outcome of patient survival was associated with low expression of POU5F1P4 in breast and gastric cancers." (PMID 30287838, 2018). "The data showed that POU5F1P4 was over-expressed in several cancer tissues including brain and CNS (central nervous system), colorectal, kidney and other cancers compared to in their normal tissues, whereas lower expression was observed in breast and gastric cancer than in their normal tissues." (PMID 30287838, 2018). "Similar survival patterns were observed for gastric cancer patients with OCT4/POU5F1P3, OCT4/POU5F1P4, POU5F1P1/POU5F1P3, POU5F1P1/POU5F1P4, or POU5F1P3/POU5F1P4 co-occurrence." (PMID 30287838, 2018).
germ cell tumor (1 paper, 2016). A benign or malignant, gonadal or extragonadal neoplasm that originates from germ cells. "We found a correlation between PIM1/2 expression and VENTX, SOX15, UTF1, NANOG, POU5F1P4, POU5F1P3, and POU5F1B expression in male germ cell tumors." (PMID 27901106, 2016).
metastatic colorectal cancer (1 paper, 2026). "Furthermore, lncRNA POU class 5 homeobox 1 pseudogene 4 (POU5F1P4) was found to be down-regulated in cells that developed resistance to cetuximab, as well as in metastatic colorectal cancer patients who were resistant to cetuximab treatment." (PMID 41362671, 2026).
ovarian carcinoma (1 paper, 2018). A malignant neoplasm originating from the surface ovarian epithelium. "Moreover, patients with low/low or low/high co-expression of OCT4/POU5F1P4 appeared to have significantly poorer survival than that of the other groups of ovarian cancer patients." (PMID 30287838, 2018). "Additionally, in ovarian cancer, OCT4 was co-expressed with DNAJBI3, C2orf88, and several genes with lower correlation values compared to the three pseudogenes (POU5F1P1, POU5F1P3, and POU5F1P4) at seminoma." (PMID 30287838, 2018).
seminoma (1 paper, 2018). A radiosensitive malignant germ cell tumor found in the testis (especially undescended), and extragonadal sites (anterior mediastinum and pineal gland). "OCT4 was found to be highly co-expressed with its three pseudogenes (POU5F1P1, POU5F1P3, and POU5F1P4) in seminoma." (PMID 30287838, 2018).
cancer (1 paper, 2018). A tumor composed of atypical neoplastic, often pleomorphic cells that invade other tissues. "Furthermore, the interactions among OCT4, POU5F1P1, POU5F1P3, and POU5F1P4 might be associated with the progression of various types of cancers." (PMID 30287838, 2018). "Among the eight pseudogenes, we selected three pseudogenes (POU5F1P1, POU5F1P3, and POU5F1P4) along with OCT4 for bioinformatics analysis because of their expression availability in various cancers." (PMID 30287838, 2018). "The results of our systematic analysis agree with studies showing that OCT4 and its pseudogenes (POU5F1P1, POU5F1P3, and POU5F1P4) are expressed in various cancer cells and affected patient survival." (PMID 30287838, 2018). "Among them, we examined OCT4 and three pseudogenes (POU5F1P1, POU5F1P3, and POU5F1P4) because of their high expression possibility in cancer." (PMID 30287838, 2018). "We then overviewed the prognostic value of POU5F1P4 expression in various cancer types." (PMID 30287838, 2018). "Here, we aimed to confirm whether POU5F1P4 was differentially expressed in various cancer types using the Oncomine database." (PMID 30287838, 2018). "Therefore, POU5F1P4 may influence cancer development by regulating OCT4 expression." (PMID 30287838, 2018).
POU5F1P4 also shares sentences with these, for which no sentence is quoted: hepatocellular carcinoma (1 paper); kidney cancer (1).